CHFR (checkpoint with forkhead and ring finger domains)
Description:
E3 ubiquitin-protein ligase that functions in the antephase checkpoint by actively delaying passage into mitosis in response to microtubule poisons. Acts in early prophase before chromosome condensation, when the centrosome move apart from each other along the periphery of the nucleus. Probably involved in signaling the presence of mitotic stress caused by microtubule poisons by mediating the 'Lys-48'-linked ubiquitination of target proteins, leading to their degradation by the proteasome. Promotes the ubiquitination and subsequent degradation of AURKA and PLK1. Probably acts as a tumor suppressor, possibly by mediating the polyubiquitination of HDAC1, leading to its degradation. May also promote the formation of 'Lys-63'-linked polyubiquitin chains and functions with the specific ubiquitin-conjugating UBC13-MMS2 (UBE2N-UBE2V2) heterodimer. Substrates that are polyubiquitinated at 'Lys-63' are usually not targeted for degradation, but are rather involved in signaling cellular stress.
Synonyms: RNF196; FLJ10796; RNF116
Tractability: Small molecule: a structure with a bound ligand is known. PROTAC: UniProt records ubiquitination sites on it; ubiquitination databases record sites on it.
Gene: Protein-coding gene on chromosome 12 (132,822,187 to 132,956,304, reverse strand). Ensembl gene ENSG00000072609.
Subcellular location: Nucleus, PML body
Subcellular location (Human Protein Atlas): Microtubules; Nuclear bodies
Gene Ontology:
Molecular function: nucleotide binding; protein binding; ubiquitin-protein transferase activity; ubiquitin protein ligase activity
Biological process: meiotic spindle checkpoint signaling; mitotic G2/M transition checkpoint; ubiquitin-dependent protein catabolic process; mitotic cell cycle; protein ubiquitination
Cellular component: nucleus; PML body
Genetic constraint (gnomAD): Loss-of-function variants: 44 observed, 60.92 expected, observed/expected ratio (o/e) 0.72, 90% interval 0.57 to 0.93. The upper end of that interval is the gene's LOEUF score, 0.93, which puts it in group 3 of 6, group 1 being the genes least tolerant of losing a copy. Missense variants: 686 observed, 717.37 expected, observed/expected ratio (o/e) 0.96, 90% interval 0.9 to 1.02. Synonymous variants: 335 observed, 297.74 expected, observed/expected ratio (o/e) 1.13, 90% interval 1.03 to 1.23.
Homologues: Orthologues: chimpanzee CHFR (99% identical), macaque CHFR (93% identical), guinea pig CHFR (84% identical), dog CHFR (84% identical), pig CHFR (83% identical), rabbit CHFR (82% identical), mouse Chfr (82% identical), rat Chfr (82% identical), tropical clawed frog chfr (66% identical), zebrafish chfr (53% identical).
Diseases named in the same sentence as CHFR in open-access papers:
CHFR is named in the same sentence as 57 diseases in open-access papers, as found by Europe PMC text mining. Sharing a sentence is not in itself a finding about the gene and the disease. The quoted sentences say what the papers report.
gastric cancer (15 papers, 2007 to 2025). A primary or metastatic malignant neoplasm involving the stomach. "Although dozens of studies focusing on CHFR have been published, little is known about its roles and the underlying mechanisms in progression of cancers including gastric cancer." (PMID 37024798, 2023). "Tumor suppressor gene CHFR (The Checkpoint with Forkhead-associated and Ring finger domains) is a mitotic checkpoint and frequently hypermethylated in gastric cancer." (PMID 37024798, 2023). "In colorectal cancer (CRC) and gastric cancer, CHFR inactivation is associated, however, with microsatellite instability (MSI) and MLH1 promoter CpG island methylation." (PMID 24375389, 2014). "The functional inactivation of CHFR due to promoter methylation and the consequent loss of mRNA expression is frequently observed in human colon and gastric cancers, suggesting its possible role also as a tumor suppressor." (PMID 18335050, 2008). "Scolnik and Halazonetis were the first to report the lack of CHFR gene in colorectal cancer and neuroblastoma cell lines, after then loss of CHFR expression has been observed in a variety of malignancies such as colorectal cancer, gastric cancer, esophageal cancer and NSCLC." (PMID 29312643, 2017). "In a small study of 12 patients with advanced stage gastric cancer that received adjuvant paclitaxel, CHFR promoter CpG island methylation was associated with a better clinical response compared to cancers with unmethylated CHFR of which the majority showed progressive disease." (PMID 24375389, 2014). "In this study, we tried to further elucidate the role and mechanism for CHFR in gastric cancer (GC) by constructing CHFR stably expressed cell lines." (PMID 37024798, 2023). "As a tumor suppressor gene, CHFR plays an important role in tumor progression and metastasis, as seen in gastric cancer, pancreatic cancer, and esophageal adenocarcinoma." (PMID 34539751, 2021). "The downregulation of CHFR is also correlated with poor prognosis in lung cancer, colon cancer, and gastric cancers." (PMID 32943033, 2020). "In vitro evidence using nasopharyngeal carcinoma, colorectal cancer, esophageal, endometrial cancer, and gastric cancer cell lines suggests that CHFR hypermethylation contributes to docetaxel and paclitaxel sensitivity." (PMID 29614786, 2018). "Our data revealed that the frequency of CHFR promoter methylation was higher in gastric cancer than in normal gastric tissue, Odd Ratio (OR) was 10.12 with 95% CI 5.17–19.79, p < 0.00001." (PMID 29515792, 2018). "Recent studies have reported the relationship of CHFR promoter methylation with clinicopathological significance of gastric cancer." (PMID 29515792, 2018). "We pooled 15 studies including 827 gastric cancer patients and conducted a meta-analysis to investigate the clinicopathological significance of CHFR promoter methylation in gastric cancer." (PMID 29515792, 2018). "The CHFR protein comprises fork head associated- (FHA) and RING-finger (RF) domain and is frequently downregulated in human colon and gastric cancers up to 50%." (PMID 18335050, 2008). "Histones H3 and H4 were deacetylated in gastric cancer cell lines showing aberrant methylation of CHFR, a mitotic checkpoint gene, suggesting a role for histone deacetylation in methylation-dependent gene silencing." (PMID 18425214, 2007). "Our previous study found CHFR played a certain extent pro-tumor function in gastric cancer." (PMID 37024798, 2023). "Next, the activation of ERK in CHFR stably expressed gastric cancer cells were detected." (PMID 37024798, 2023). "Therefore, we firstly examined the activation of AKT under CHFR overexpression in gastric cancer cells and unexpectedly the result indicated that the ectopic expression of CHFR significantly elevated the phosphorylation of AKT in SGC-7901 and AGS cells." (PMID 37024798, 2023).
gastric cancer (continued). "Our previous data also unveiled that CHFR could promoted cell migration and invasion of gastric cancer cells in which CHFR was transiently overexpressed using plasmid, but leaving the molecular mechanism to be further documented." (PMID 37024798, 2023). "As a well-known negative regulator of cell cycle progression, CHFR was regarded as a tumor suppressor gene and hypermethylation in CHFR gene promoter were frequently observed in multiple cancer types, such as colorectal cancer and gastric cancer." (PMID 37024798, 2023). "Taken together, our findings suggested that CHFR might take part in gastric cancer progression especially cancer metastasis by activating AKT and ERK via NRF2- ROS axis." (PMID 37024798, 2023). "Given that CHFR is highly methylated and silenced in G2/M phase in gastric cancer, it is speculated that CHFR is an E3 ubiquitin ligase for ZEB1 and exerts its tumor suppression through destabilizing ZEB1 in TNBC." (PMID 34462429, 2021). "Similarly, the downregulation of CHFR in gastric cancer patients makes them more sensitive to docetaxel exposure." (PMID 32943033, 2020). "We concluded that CHFR could serve as a biomarker for diagnosis of gastric cancer, and a drug target for development of gene therapy in gastric cancer." (PMID 29515792, 2018). "Additionally, the rate of CHFR promoter methylation was significantly increased in high grade of gastric cancer compared to low grade, OR was 1.64 with 95% CI 1.00–2.68, p = 0.05." (PMID 29515792, 2018). "On the other hand, some research proved that downregulation of CHFR could also exerts anti-tumor functions such as sensitizing gastric cancer to PARP inhibitor, and impairing the cell migration and invasion potential in gastric cancer cell lines which was reported by our previous study." (PMID 37024798, 2023). "Therefore, we next examined whether CHFR could take part in the regulation of ROS generation in gastric cancer." (PMID 37024798, 2023). "Therefore, it looks like that CHFR is not an absolute tumor suppressor at least in gastric cancer which was supported by the data from datasets of Kaplan Meier Plotter that CHFR expression was negatively associated with the overall survival rate of gastric cancer patients." (PMID 37024798, 2023). "Later it became clear that CHFR promoter CpG island methylation occurs in other cancers as well, among which CRC (24–53 %) and gastric cancer (35–52 %)." (PMID 24375389, 2014). "In advanced gastric cancer patients, CHFR methylation was not predictive of response to docetaxel or paclitaxel." (PMID 29614786, 2018). "Multiple studies have shown that CHFR promoter CpG island methylation can be detected not only in the primary cancers but also in blood (NSCLC), stool (CRC) and peritoneal fluid (gastric cancer)." (PMID 24375389, 2014). "However, our published research indicated that there is a negative relevance between CHFR expression level and overall survival rate of gastric cancer patients, and enhanced the cell migration and invasion of GC cells." (PMID 37024798, 2023).
colorectal cancer (14 papers, 2007 to 2023). A primary or metastatic malignant neoplasm that affects the colon or rectum. "The expression of CHFR was found to be downregulated by promoter methylation or mutated in various cancers such as colorectal cancer, esophageal cancer, human non-small-cell lung cancer, GC." (PMID 37024798, 2023). "On the other hand, CHFR promoter methylation is also associated with increased taxane sensitivity in colorectal cancer, gastric cancer, and nonsmall cell lung cancer." (PMID 34885153, 2021). "CpG island methylation within the CHFR promoter is associated with a poor prognosis in multiple cancer types, including microsatellite stable colorectal cancer." (PMID 34885153, 2021). "Thereby, it was shown that polymorphisms in the CHFR gene can be used as indicator for colorectal cancer susceptibility." (PMID 24375389, 2014). "In colorectal cancer, an association between CHFR promoter CpG island methylation and poor prognosis has been reported in two independent studies." (PMID 24375389, 2014). "Moreover, some studies have shown an inverse correlation between the loss of CHFR function and Aurora A levels in CHFR-/- mouse embryonic fibroblasts, in prostate and breast cancer cell lines models, and also in colorectal cancer tissue samples." (PMID 34869418, 2021). "The previously reported association between CHFR promoter methylation and response to taxanes in lung, gastric and colorectal cancer certainly raises the possibility that CHFR protein levels might predict taxane sensitivity in other tumor types." (PMID 34885153, 2021). "The Checkpoint with Forkhead-associated and Ring finger domains (CHFR) is a mitotic checkpoint and tumor-suppressor gene, its loss contributes tumorigenesis of epithelial cancers including colorectal carcinoma (CRC)." (PMID 29179506, 2017). "As it was reported that combination of both TSA and 5-aza-2’-deoxycytidine (5-aza-dC) reactivate the transcription of CHFR in RKO colorectal cancer cells, we assessed the effect of those agents on CHFR mRNA level in TNBC cells." (PMID 34462429, 2021). "Scolnick and Halazonetis first described the inactivation of CHFR in neuroblastoma and colorectal cancer cell lines." (PMID 29179506, 2017). "Concurrent promoter methylation in NEUROG1 and CDKN2A (p16) was associated with poor DFS in stages II and III colorectal cancer patients, and CHFR promoter methylation indicated poor prognosis in stage II colorectal cancer patients." (PMID 26157509, 2015). "CHFR promoter methylation has, however, been described in other types of cancer, such as breast, gastric and colorectal cancer." (PMID 17971771, 2007). "CHFR gene is silenced by promoter hypermethylation or mutated in several primary tumors such as 20% in NSCLC, 30% in esophageal cancer, and 40% in colorectal cancer (CRC)." (PMID 29515792, 2018). "CHFR promoter hypermethylation has been observed in several tumors such as 30% in esophageal cancer, 20% in NSCLC and 40% in colorectal cancer (CRC)." (PMID 29312643, 2017). "Previous study showed that 5-aza-dC alone, but not TSA, upregulate mRNA level of CHFR in colorectal cancer; on the contrary, we found that only TSA could upregulate CHFR protein level in TNBC cells instead of mRNA level." (PMID 34462429, 2021).
esophageal cancer (11 papers, 2013 to 2023). A primary or metastatic malignant neoplasm involving the esophagus. "In esophageal adenocarcinomas (EAC), CHFR DNA copy number loss appears to occur in 59 % (17/27) of esophageal cancers and is associated with reduced CHFR expression." (PMID 24375389, 2014). "Taken together, results of the present study indicate that aberrant hypermethylation of CpG islands is the key mechanism associated with transcriptional inactivation of the CHFR gene in patients with esophageal cancer." (PMID 24348823, 2014). "Re-expression of CHFR induced G2/M phase arrest and increased resistance to docetaxel in esophageal cancer cells." (PMID 26967246, 2016). "In this study, we compared the methylation status of CHFR and the sensitivity of esophageal cancer cells to paclitaxel, docetaxel, VP16 and cisplatin." (PMID 25821560, 2015). "In our study, silencing CHFR by promoter region hypermethylation sensitized esophageal cancer cells to docetaxel and paclitaxel." (PMID 25821560, 2015). "To understand the mechanism of promoter region methylation in cheom-sensitivity, we analyzed the cell cycle phase changes in CHFR methylated esophageal cancer cell lines before and after docetaxel/paclitaxel treatment, with or without 5-AZ." (PMID 25821560, 2015). "In CHFR methylated esophageal cancer cells, under docetaxel or paclitaxel treatment, S and G2/M phase cells were increased with the treatment of 5-AZ (all p<0.05)." (PMID 25821560, 2015). "We found CHFR methylation sensitizes esophageal cancer cells to docetaxel and paclitaxel, and 5-AZ induces chemoresistance of CHFR methylated cells to docetaxel and paclitaxel." (PMID 25821560, 2015). "CpG island hypermethylation of the promoter region in the CHFR gene is a key mechanism involved in silencing the CHFR gene in patients with esophageal cancer." (PMID 24348823, 2014). "It has been reported that CHFR expression levels are downregulated in various digestive cancers, including esophageal cancer." (PMID 24348823, 2014). "Hypermethylation of the CHFR gene is a common event in the development of primary esophageal cancer." (PMID 24348823, 2014). "CHFR promoter CpG island methylation and subsequent transcriptional silencing was first described in esophageal cancer, of which 16.3 % (7/43) was hypermethylated while this was absent in adjacent normal tissues." (PMID 24375389, 2014). "Previous studies have revealed that CHFR expression levels are frequently downregulated in patients with digestive cancer, including esophageal cancer." (PMID 24348823, 2014). "The results indicate that aberrant methylation of the CHFR gene is frequently (44.8%) observed in esophageal cancer." (PMID 24348823, 2014). "Methylation of CHFR is a late stage event in esophageal cancer." (PMID 25821560, 2015). "To determine if CHFR methylation may serve as an early detection marker of esophageal cancer, we examined the methylation of CHFR in normal esophageal mucosa, different grades of dysplasia, and in invasive cancer." (PMID 25821560, 2015). "Methylation of CHFR sensitized esophageal cancer cells to docetaxel and paclitaxel." (PMID 25821560, 2015). "Esophageal cancers exhibited a variety of levels of CHFR gene expression." (PMID 24348823, 2014). "Aberrant hypermethylation of the CHFR gene was observed in 13 of 29 primary esophageal cancers." (PMID 24348823, 2014). "CHFR has been found to be either lost or down regulated or its promoter being hypermethylated in several human cancers including breast, prostate, lung and esophageal cancers." (PMID 24012691, 2013). "In addition, CHFR expression was induced by 5-AZ in CHFR methylated esophageal cancer cells." (PMID 25821560, 2015). "Previously, aberrant methylation of the CHFR gene associated with gene silencing has been demonstrated in several studies, although it has not been fully clarified how the CHFR gene is regulated in esophageal cancer." (PMID 24348823, 2014).
esophageal cancer (continued). "CHFR is methylated in CRC (24–53%), gastric cancer (35–52%), esophageal cancer (16.3%) and NSCLC (10–40%)." (PMID 26967246, 2016). "Our results also revealed that CHFR expression levels do not have prognostic significance in patients with esophageal cancer." (PMID 24348823, 2014). "To date, a single study has been performed to investigate the correlation between CHFR expression and patient characteristics in esophageal cancer, and indicated no relative clinical factors." (PMID 24348823, 2014). "The clinical importance of CHFR expression in esophageal cancer is not well studied." (PMID 24348823, 2014). "However, the role of CpG island methylation in CHFR silencing in esophageal cancer has not been fully investigated." (PMID 24348823, 2014).